GPR84 (G protein-coupled receptor 84)
Diseases named in the same sentence as GPR84 in open-access papers (continued):
Sharing a sentence is not in itself a finding about the gene and the disease.
tumor (continued). "Moreover, we found that IL-11 at least partly inhibited the expression of GPR84 in the tumor microenvironment through the inactivation of STAT1." (PMID 36593458, 2023). "Flow cytometry revealed that the proportions of MDSCs were significantly reduced in the spleen, tumor, and blood of GPR84−/− tumor-bearing mice compared to the wild-type (WT) group, whereas CD8+ T cells were remarkably increased in GPR84−/− tumor-bearing group." (PMID 37105980, 2023). "In addition, the proportions of activated CD8+CD69+ T cells were clearly increased in the tumor tissues, blood, and spleen of GPR84−/− mice." (PMID 37105980, 2023). "GPR84 blockade inhibits tumor progression by remodeling the immunosuppressive microenvironment." (PMID 37105980, 2023). "Second, our interesting finding of GPR84 as a potential drug target came from differential expression analysis, lacking more direct evidence as to how GPR84 is linked to tumor cell proliferation." (PMID 36061172, 2022). "Hence, the over-representation of beneficial commensals in an animal husbandry might innately induce an anti-tumor response via GPR84 activation, obscuring any add-on effects using activating agonists." (PMID 39859206, 2025). "Importantly, the tumor growth curve showed significant suppression in GPR84−/−→WT group." (PMID 37105980, 2023). "Ultimately, we demonstrate proof-of-concept translational study that the GPR84 agonist, 6-OAU, can modulate polarization of TAMs and provoke profound anti-tumor immunity, which enhances the efficacy of ICB therapy." (PMID 38349405, 2024). "Differential expression analysis between macrophages from the tumor and normal tissue identified genes that are enriched specifically within TAMs (TREM2, GPR84 and SPP1) and tissue-resident macrophages (LYVE1), which is consistent with previous observation." (PMID 38349405, 2024). "Third, GPR84 regulates the recruitment and function of neutrophils, highlighted as pivotal regulatory cells modulating the TME and the anti-tumor immunity." (PMID 38349405, 2024). "The GPR84 selective antagonist restored the proliferation ability and antitumor immunity of CD8+ T cells, thereby delaying tumor progression in mouse models." (PMID 37105980, 2023). "We found that the expression of GPR84 in BMMs was gradually downregulated during bone metastasis of CRC, and the activation of GPR84 significantly prevented osteoclastogenesis in the tumor microenvironment." (PMID 36593458, 2023). "Beginning on day 113 of tumor induction with 4-NQO, the WT, and GPR84−/− groups were treated with anti-PD-1 or IgG every three days." (PMID 37105980, 2023). "As a result, GPR84, NCF2, HK3, LILRB2, and CCL18 significantly affected the overall survival (OS) of GBM patients (multivatiate Cox p < 0.05), of which the protein level of GPR84 and NCF2 was significantly increased in the tumor core region." (PMID 36177003, 2022). "In summary, despite the systemic uptake of ZQ-16, the GPR84 agonist was not able not reduce tumor growth in the subcutaneous MC38 tumor injection model." (PMID 39859206, 2025). "Extending this observation, our analysis of 13 tumor types revealed that mRNA levels of GPR84 are restricted to macrophages from the tumor, but not adjacent benign and other tissues." (PMID 38349405, 2024). "Furthermore, the expression or activity of MDSCs-associated molecules (ARG1, CYBB, iNOS, IL-10, NCF4, and TGF-β2) were significantly decreased from GPR84−/− mice in both LLC and B16F0 tumor models." (PMID 37105980, 2023). "Through analysis of single-cell RNA sequencing (scRNA-seq) datasets from several clinical studies, we identified one fatty acid sensor, G-protein-coupled receptor 84 (GPR84) is uniquely enriched in tumor-infiltrating myeloid cells but not abundant in other immune cells nor in normal tissue." (PMID 38349405, 2024). "Consequently, activating GPR84 pharmacologically not just produces profound anti-tumor immunity but also synergizes with PD-1 blockade." (PMID 38349405, 2024).
tumor (continued). "Mice lacking GPR84 exhibited more aggressive tumor growth than littermate control Gpr84+/+." (PMID 38349405, 2024). "Moreover, the expression of functional molecule derived from CD4+ T cells or CD8+ T cells in GPR84−/− tumor-free mice was not different from that of WT mice." (PMID 37105980, 2023). "In summary, the ADCP assay indicated that the GPR84 agonists 6-OAU and ZQ-16 did not increase macrophage-mediated tumor cell phagocytosis." (PMID 39859206, 2025). "In this study, we verified that GPR84 knockout did not change the proportions of MDSCs, macrophages, B cells, NK cells, CD4+T cells and CD8+ T cells in tumor-free mice." (PMID 37105980, 2023). "The expression of genes PTEN (tumor-suppressor), COPZ1 (involved in autophagy and protein trafficking), and GPR84 (G-protein coupled receptor) were not significantly altered due to vector integrations." (PMID 26052523, 2014).
infection (7 papers, 2015 to 2025). The state of being infected such as from the introduction of a foreign agent such as serum, vaccine, antigenic substance or organism. "Collectively, these findings underscore the complex role of GPR84 in immune responses to pathogenic infections." (PMID 39858878, 2025). "Utilizing Mm infections in both an in vivo mouse model and an in vitro macrophage model, we show an association between GPR84 and mycobacterial proliferation, infection-induced tissue damage, and the expression of pro-inflammatory cytokines." (PMID 39858878, 2025). "We subsequently employed an in vivo mouse tail vein infection model to evaluate the effects of Gpr84−/− mice on tissue pathology following Mm-wasabi injection into the tail vein." (PMID 39858878, 2025). "Following this, we validated these results in vitro using mice and human macrophage cell lines infected with Mm-wasabi, which similarly demonstrated a significant increase in Gpr84 mRNA expression post-infection." (PMID 39858878, 2025). "Comparative studies with expression data from Shigella-infected children demonstrate that GPR84 is also induced in humans, highlighting the translational potential of modelling human infection in zebrafish." (PMID 38131137, 2024). "This comparison revealed that several markers identified in our work, including gpr84, are also identified in response to S. flexneri infection in humans and highlights the translational potential of modelling human infection in zebrafish." (PMID 38131137, 2024). "If this scenario proves reasonable, GPR84 serves as a sensor for local bacterial load during infection." (PMID 36164652, 2022). "First, the mechanisms by which GPR84 functions following infection may differ depending on the diseases being studied." (PMID 39858878, 2025). "Strikingly, only a discrete set of immune genes (including genes encoding the aconitate decarboxylase Acod1 and the G-protein coupled receptor Gpr84) remain differentially expressed at 24 h post-infection (hpi), suggesting an important role for these markers in host survival." (PMID 38131137, 2024). "Although the role of complement factors, chemokines, hydrolytic enzymes and aconitate dehydrogenase have been associated with a variety of infectious and inflammatory processes, the precise role of gpr84 during infection was mostly unknown." (PMID 38131137, 2024). "Thus, it appears plausible that GPR84-expressing innate immune cells, recruited to the site of infection, induce further pro-inflammatory responses when the bacterial load, and with that the concentration of GPR84-activating QS molecules, is high." (PMID 36164652, 2022). "Since Gpr84 is induced in both microglia and astrocytes, this frameshift deletion could affect the responses of glial cells to infection in these mouse strains." (PMID 26214311, 2015). "Consequently, while it appears that GPR84 plays an important role in the immune response to infections, its functions are complex and may vary depending on the pathogen, the disease model, the time of the response, and the specific cell type examined." (PMID 39858878, 2025). "Next, we explored GPR transcript changes during Mtb infections with publicly available data, and GPR84 is significantly upregulated among RAW264.7 infected with different MOIs and H37Rv-infected AM at early time points of infection (4 h or 2 h)." (PMID 39858878, 2025). "Furthermore, the ligand for GPR84 and whether mycobacterium harbors GPR84-specific pathogen-associated molecular patterns (PAMPs), like PDIM and Sulfolipids, or other virulence factors that may affect lipid metabolism pathways or macrophage polarization to promote infection remains to be determined." (PMID 39858878, 2025). "We observed that at an early time point post infection, Gpr84−/− mice showed an increased expression of pro-inflammatory cytokines, suggesting that GPR84 may inhibit their expression in the early stages of infection." (PMID 39858878, 2025).
infection (continued). "While the extent and magnitude of gene expression changes were not as robust as the virulent ZIKV-MR766 infection model, we nevertheless saw significant changes in the expression of 7 of 14 genes analyzed, including Adora2, Cacna1e, Ccl5, Gpr84, Nlgn1, Pmch, and Tor3a." (PMID 35462541, 2022).
metabolic disease (6 papers, 2018 to 2024). A congenital disorder (due to inherited enzyme abnormality) or acquired (due to failure of a metabolically important organ) disorder resulting from an abnormal metabolic process. "In the context of metabolic disease, it has been suggested that GPR84 may influence lipid metabolism, as, compared to normal mice, GPR84-deficient mice exhibited smaller livers and increased triglyceride accumulation in response to FFA diet." (PMID 29973940, 2018). "The role of GPR84 in inflammatory and metabolic disease have been known for some time, but more recently a role in fibrotic disease has begun to emerge." (PMID 33960725, 2021). "Our structures could also facilitate rational drug discovery against inflammation and metabolic disorders targeting GPR84." (PMID 37277332, 2023). "In addition, GPR84 influences lipid metabolism in metabolic diseases." (PMID 37856216, 2023).
degenerative diseases (2 papers, 2017 to 2023). "Further development of both agonists and antagonists will provide increased understanding of GPR84 function as well as therapeutic tools for neuronal inflammatory, traumatic, and degenerative diseases." (PMID 28974234, 2017).
bacterial infections (1 paper, 2022). "Unfortunately, local concentrations of cis-2-C10 and trans-2-C10 at the side of bacterial infections are unknown so far but should be studied in detail together with GPR84-related functionalities in vivo." (PMID 36164652, 2022).
immune disorder (1 paper, 2015). "In the present study, JQ1 also significantly inhibited Mmp13, Clec5a, and Gpr84 expression, and these inhibitory effects of JQ1 may play a potential role in immune disorder treatment, possibly through inhibition of macrophages and the ensuing inflammatory responses." (PMID 26582142, 2015).
infectious disease (1 paper, 2022). A disorder directly resulting from the presence and activity of a microbial, viral, or parasitic agent in humans. "In summary, our results suggest that infectious disease-causing microbial pathogens exert selective pressures on GPR84 as an immune cell receptor conserved for the recognition of bacteria-derived QS molecules." (PMID 36164652, 2022).
GPR84 also shares sentences with these, for which no sentence is quoted: Hypercholesterolemia (2 papers); prostate carcinoma (2); breast carcinoma (1); cardiac ischemia (1); cardiovascular disease (1); Cerebral ischemia (1); cognitive decline (1); COVID-19 (1); esophageal squamous cell carcinoma (1); glioma (1); hyperlipidemia (1); kidney cancer (1); leukemia (1); liver cancer (1); neurological disorders (1); osteoarthritis (1); pancreatic cancer (1); Parkinson disease (1); Shock (1); stomach cancer (1); xeroderma pigmentosum (1).